MPO (myeloperoxidase)
Diseases named in the same sentence as MPO in open-access papers (continued):
Sharing a sentence is not in itself a finding about the gene and the disease.
infection (continued). "Furthermore, IVM and MPO assays revealed that neutrophil recruitment starts after 3 days of infection." (PMID 34858432, 2021). "MPO is an enzyme released by activated neutrophils during an infection." (PMID 35011845, 2021). "Together with a higher expression of myeloperoxidase (MPO) this may have made males more resilient to infection with S. epidermidis." (PMID 33643975, 2021). "Before S. suis (1.25 × 105 CFU) infection, a prophylactic dose of AnxA1 (25 or 50 μg/kg of body weight) was given to WT and Fpr2−/− mice via the intravenous (i.v.)route, after which neutrophil counts and MPO levels were measured." (PMID 33318141, 2021). "Particularly, on D39, myeloperoxidase gene was still enhanced after 35 h post-infection." (PMID 34295335, 2021). "CXCL8 and MPO levels in the peripheral blood do not differ with infection status nor associate with birth outcomes." (PMID 34737733, 2021). "MPO as part of NETs is an important component of the immune response to infection in vivo." (PMID 33916434, 2021). "In this in vitro study, we evaluated the effects of TG6-44, a novel quinazolin-derived myeloperoxidase-specific ROS inhibitor, on influenza A virus (A/X31) infection using THP-1 lung monocytic cells and freshly isolated peripheral blood mononuclear cells (PBMC)." (PMID 34280220, 2021). "In response to infection and injury, neutrophils form extracellular traps (NETs), consisting of a tight network of nuclear material, lined with cytotoxic proteins such as myeloperoxidase (MPO) and neutrophil elastase (NE)." (PMID 33717100, 2021). "In addition to acute phase proteins, we also observed increases in IgM and MPO in a subset of infections." (PMID 32253915, 2020). "In contrast, MPO, which serves in whole blood as a surrogate for neutrophil count, was frequently increased at the earliest stage of infection followed by spikes every 2 or 3 days, consistent with periodic release from and regeneration of neutrophil pools in the bone marrow." (PMID 32253915, 2020). "Among animal models, the role of myeloperoxidase has been emphasized mainly in mice, where experiments with MPO-deficient mice showed their susceptibility to Candida albicans and Klebsiella pneumoniae infection." (PMID 32899838, 2020). "Given that MPO is a potent bactericidal, inhibition of MPO systemically may lead to an increase in infections." (PMID 33569056, 2020). "The activity of myeloperoxidase (MPO), mostly expressed in neutrophils, was also significantly increased in the lung homogenates of IL-10-deficient mice with A. baumannii infection at 1 and 3 days after infection." (PMID 32153580, 2020). "MPO is mainly synthesized and expressed in neutrophils and MPO activity often serves as an indicator of activation and accumulation of neutrophils in the site of infection." (PMID 32581788, 2020). "Finally, a large number of dermal TRMs became positive for the neutrophil marker MPO during infection, while this number was reduced in neutrophil depleted mice." (PMID 33137149, 2020). "Histologic evaluation of skin samples neighboring IL-1β-loaded pumps at the peak of infection revealed extracellular MPO lining of the contact regions as well as intra- and extracellular citrullinated histones in the tissues surrounding the contact regions with the pumps." (PMID 31156635, 2019). "In addition to the role of MPO in antibacterial defence, it is also an important enzyme regulating the migration of neutrophils to sites of infection and inflammation, primarily by mediating H2O2 flux." (PMID 31002727, 2019). "Increased MPO level may strengthen ability to resist infection, however, it may also increase the synthesis of hypochlorous acid, which can be detrimental to normal tissue." (PMID 31798456, 2019). "Therefore, infection with each of the three strains triggered in the same manner the extracellular release of myeloperoxidase and elastase by human neutrophils." (PMID 31134162, 2019).
infection (continued). "The release of autoantigens (including PR3 and MPO) by neutrophils at sites of infection might also affect the maintenance of tolerance." (PMID 31358739, 2019). "The production of elastase and MPO are part of the antimicrobial arsenal of Mφ to fight infection." (PMID 31412039, 2019). "To evaluate degranulation, we examined the release of MPO and Neutrophil elastase, which are both azurophilic granule contents, by neutrophils isolated from the 14 healthy donors in the culture medium upon their infection by the different Leishmania strains." (PMID 31134162, 2019). "The incremented release of MPO, along with the increased number of circulating neutrophils ready to go to the site of infection observed after rbG-CSF treatment, could improve the ability of cows to prevent clinical disease during periparturient period." (PMID 31640199, 2019). "In addition, lung MPO activity was measured as a surrogate for lung neutrophil content, where levels were increased by SP-infection and reduced to control levels by 1A8-mediated neutrophil depletion." (PMID 31776393, 2019). "To determine whether the neutrophil response to infection is affected by expression of lyz:MPO-mEmerald, we used an otic vesicle infection model to investigate neutrophil recruitment." (PMID 31002727, 2019). "In our study, an increase in the MPO activity was observed in the liver of MAYV-infected mice at all times post-infection." (PMID 31653913, 2019). "For example, in an in vivo hind-paw mouse model of diabetic wound infection with methicillin-resistant S. aureus (MRSA), combining bacteriophage with linezolid showed a marked reduction in myeloperoxidase (MPO) levels (after 5 days of infection), as compared to either agent alone." (PMID 31052335, 2019). "Noticeably, PC1 mostly segregated the non-infected vs. infected populations and PC2 distinguished the infection parameters (infection index, percentage of infection, oxidative burst, Elastase, and MPO) vs. the cytokines IL-6, IL-10, IL1-β, and TNF-α production." (PMID 31134162, 2019). "However, despite the presence of neutrophil-derived MPO at sites of infection in a potentially “dangerous” immunological context, the links between the loss of tolerance to MPO and microbial-derived peptides are unclear." (PMID 31358739, 2019). "Thus, neutrophil recruitment at the infection site of skin was estimated by determining MPO activity." (PMID 29887858, 2018). "By perturbing the relative abundance of neutrophils and macrophages during conidial inoculation, we demonstrate that the macrophage intracellular niche favours infection establishment by protecting conidia from a myeloperoxidase-dependent neutrophil fungicidal activity." (PMID 29883484, 2018). "Once neutrophils reach the site of infection their primary role is to kill invading microbes by production of reactive oxygen species (ROS) and the release of antimicrobial proteins such as myeloperoxidase (MPO) and human neutrophil elastase (HNE) in a process of degranulation." (PMID 30283445, 2018). "MPO-specific bioluminescence was also investigated in the initial stages of infection." (PMID 29097502, 2018). "In our study, the MPO activity increased only in the duodenum at 12 h of infection." (PMID 29324806, 2018). "Additionally, ETEC (Group III) infection was associated with lower concentrations of AAT at Age 1 and higher concentrations of MPO in older Age 2 children." (PMID 28396264, 2017). "The number of PMN infiltrating the cornea after infection was quantitated by MPO assay." (PMID 28961278, 2017). "Five days post infection with T. spiralis, chitosan appeared to influence the levels of myeloperoxidase (MPO) and cytokines in mice: higher levels of MPO, MCP-1, TNF-α, IL-12p70, IL-6, IL-10 and TGF-β were found in infected mice treated with chitosan compared to those who were not." (PMID 29156562, 2017). "However, P. gingivalis significantly reduced the MPO product, bactericidal HOCl, in early times of infection upon eATP stimulation." (PMID 28725637, 2017).
infection (continued). "Whereas gp91phox and MPO expression remained unchanged, the infection led to an induction of iNOS." (PMID 28697801, 2017). "Intriguingly, GECs significantly increase MPO activity in response to exogenous ATP treatment and P. gingivalis infection whereas the data also demonstrate a significant decrease in the downstream MPO reaction product, HOCl, in the presence of infection and ATP." (PMID 28725637, 2017). "Interestingly, neutrophil number and activation at the site of infection were suppressed as assessed by fecal lipocalin-2, myeloperoxidase activity and neutrophil number despite more tissue damage by E. histolytica in antibiotic pre-treated mice." (PMID 28817707, 2017). "Therefore, we infected in vitro generated murine neutrophils with defects in NADPH-oxidase, MPO and iNOS with A. phagocytophilum and compared the course of infection to it in wild-type cells." (PMID 28697801, 2017). "Twenty-four hours post infection myeloperoxidase (MPO) and neutrophil elastase (NE) levels were found to be significantly higher and increased numbers of neutrophils were observed by immuno-histochemistry in the lungs of clodronate treated mice as compared to those receiving control liposomes)." (PMID 27739519, 2016). "Interestingly, MPO activity was higher in gp91phox−/− footpads than in WT at 6 and 72 h post-infection." (PMID 27056545, 2016). "More interestingly, MPO activity persisted 72 h after infection." (PMID 27056545, 2016). "Mice lacking myeloperoxidase (MPO), an enzyme associated with neutrophil antimicrobial activity, succumb to the infection faster than WT mice upon infection with C. neoformans either intranasally or intravenously." (PMID 26903984, 2016). "Secondary infection with serotype 3 exhibited the next highest MPO activity." (PMID 27034012, 2016). "MPO activity was generally elevated for all wild-type infections compared to capsule mutant." (PMID 27034012, 2016). "Second, neutrophil priming by cytokines (e.g., TNF), which may occur after infection-related stimuli, leads to MPO exposure on the cell surface, allowing ANCA to bind and fully activate the neutrophils." (PMID 26904693, 2016). "In gp91phox−/− mice we found more MPO activity 6 h after infection." (PMID 27056545, 2016). "Similar to humans, MPO knockout mice exhibit higher susceptibility to some, but not all infections including those caused by Candida glabrata, S. aureus, and S. pneumoniae." (PMID 26904693, 2016). "Although reports exist demonstrating that MPO-deficient patients can have a higher incidence of severe infections, the majority of patients lacking MPO have been shown not to be particularly susceptible to chronic infections." (PMID 26904693, 2016). "Consistent with microbicidal function of MPO, the MPO deficient mice were more likely than the wild-type mice to be infected or die from infection employing various models, suggesting that the MPO-dependent oxidative system is important for host defense against fungi and bacteria." (PMID 26998194, 2016). "Notably, compared to its wild-type, secondary infection with the capsule mutant showed significantly lower MPO activity, i.e. ∼5 to 6-fold lower." (PMID 27034012, 2016). "Indeed, we found that Sev infection was associated with NET formation in the lung and release of cell-free DNA complexed to myeloperoxidase in the alveolar space and plasma that peaked on day 2 post infection." (PMID 27617014, 2016). "In infection with E. coli both XO and MPO levels were increased the most." (PMID 24591758, 2014). "In accordance, whole lung MPO concentrations were lower after infection with D39ΔhtrA (P < 0.05)." (PMID 24244609, 2013). "However, combination therapy using both the agents was much more effective in arresting the entire infection process (bacterial load, lesion score, foot myeloperoxidase activity and histopathological analysis)." (PMID 23418497, 2013).
infection (continued). "MPO has been directly and indirectly linked to neoplasia and is involved not only in the production of oxidative hypochlorous acid from H2O2 during infection but also in the metabolic activation of a number of procarcinogens, which are known to be risk factors for many types of cancer." (PMID 23991124, 2013). "While the mouse has proved a valuable tool for exploring the biology of NETs in infection and inflammation models, it is important to recognize that the regulatory contributions of MPO and HOCl to the observed process appear to be markedly diminished in the murine condition." (PMID 22912772, 2012). "The results of the present study demonstrated that in vivo infection of VRSA causes alteration of oxidant-antioxidant status in spleen, as evidenced by enhanced NO, MPO, MDA, PC, and GSSG level and decreased GSH level and also SOD, CAT, GPx, GR, and GST activity." (PMID 21785683, 2011). "We found that the alloxan-treated mice showed decreased ability to totally clear the bacterial infection compared to control mice, despite a greater initial decrease of bacteria post-infection and increased number of recruited neutrophils to the infected area (MPO, p = 0.063)." (PMID 21799868, 2011). "MPO system plays an important role in the microbicidal activity of phagocytes and neutrophil play an essential role in the Human's innate immune response to infection." (PMID 20540783, 2010). "However, leukocyte infiltration and MPO levels were significantly higher in concentrated empty capsid infection as compared to mock injected corneas (p<.05) (respectively)." (PMID 20419141, 2010). "Regarding laboratory findings, the infection group exhibited higher proteinuria levels at diagnosis (1.68 g/gCr vs. 0.55 g/gCr, P = 0.03), whereas serum creatinine, estimated glomerular filtration rate (eGFR), and MPO-ANCA titers were comparable between the groups." (PMID 41408511, 2025). "The results revealed no linear relationship between MPO levels and the risk of H. pylori infection; instead, a significant U-shaped association was observed, indicating that both low and high MPO levels were linked to an increased risk of infection." (PMID 40943779, 2025). "More specifically, key therapeutic approaches to modulate neutrophil function may include targeting neutrophil development and production, inhibiting neutrophil accumulation at sites of infection or inflammation, or reducing the adverse effects of neutrophil‐derived products like NE, MPO, or NETs." (PMID 41165300, 2025). "The results of this study indicate that TMP-SMX use in older adults with MPO-AAV may not only prevent PCP but also help suppress the overall risk of infections, regardless of the type of induction therapy administered." (PMID 41408511, 2025). "Thus, according to a previously published classification we separated PJI cases into acute (n = 33, 50.7%) and low-grade (n = 32, 49.3%) infections, to observe whether the levels of MPO could be influenced by this factor." (PMID 38912350, 2024). "However, among the tested variable, only the site of arthroplasty was able to significantly influence the relationship between MPO and infection (its significance levels as a factor in ANCOVA analysis was P = 0.022, whereas for age was P = 0.9, sex P = 0.575, BMI P = 0.06)." (PMID 38912350, 2024). "In response to infection and injury, neutrophils form neutrophil extracellular traps (NETs)—high molecular weight chromatin filaments that serve as scaffolds decorated with histones and cytotoxic proteins, like myeloperoxidase (MPO) and neutrophil elastase (NE)." (PMID 38259485, 2023). "This could overcome the limitation of long-term MPO inhibitors on innate immunity and clearing infection, and provides a possible additional benefit, as SeCN− can be metabolised by cells and incorporated into selenoproteins, which have potent antioxidant abilities and improve cell survival." (PMID 36830036, 2023).
infection (continued). "Therefore, although MPO is involved in normal innate immunity, inhibiting MPO activity is unlikely to be accompanied by increased risk of infection." (PMID 37699574, 2023). "These granular enzymes vary with cell type but include elastase, myeloperoxidase, lysozyme, and cathepsin G. Various clinical studies have demonstrated that collectively, these enzymes, are sensitive and reliable markers of both early-onset phases and established infections." (PMID 36292097, 2022). "Interestingly, SIGNR1 blockade failed to improve the survival of infected MPO-deficient mice even at 100-fold lower infection doses, confirming that the beneficial impact of SIGNR1 blockade is mediated by regulating oxidative neutrophil effector function." (PMID 35945238, 2022). "To investigate whether A/J neutrophils displayed enhanced release of these mediators in the airways during infection, we assayed the presence of neutrophil elastase, MPO, and S100A8 in BAL fluid from mice at day 5 PI when lung neutrophil numbers had equilibrated between the strains." (PMID 36685578, 2022). "Moreover, inflammation measured by myeloperoxidase activity was significantly higher both in the FP and in the tail of the Ifng−/− LgyLRV1+ group consistently along the course of infection." (PMID 36034709, 2022). "Thus, target cells for MPO inhibition by ABAH were present at sites of infection." (PMID 35269694, 2022). "Interestingly, infection significantly lowered the levels of released MPO and neutrophil elastase." (PMID 35203591, 2022). "Although infection is likely to trigger the release of MPO from activated neutrophils during infection episodes, no direct evidence has linked acute infection to anti-CarP Ab-positive RA, and the risk of infection in autoantibody-mediated RA is still under investigation." (PMID 33445768, 2021). "In response to infection or inflammatory stimuli, neutrophils can form neutrophil extracellular traps (NETs), a web-like structure, which consists of DNA, histone proteins, granular proteins, such as neutrophil elastase (NE) and myeloperoxidase (MPO), and cytoplasmatic components." (PMID 34884536, 2021). "Probing for MPO by western blot of proteins derived from whole placental tissue may serve as a proxy for intensity of MPO expression, but preliminary analysis thereto does not reveal compelling evidence for influence of protein levels by infection status." (PMID 34737733, 2021). "Finally, myeloperoxidase (MPO) produces hypohalous acid in response to infection." (PMID 32411723, 2020). "In this regard, intestine IHC staining of the myeloperoxidase enzyme (MPO), which is present in neutrophil granules, showed a significant increase (p < 0.05) in neutrophil infiltration in the duodenum, ileum and colon after infection, but a decrease in the jejunum." (PMID 32218351, 2020). "Therefore, the elevation of AAT, MPO, and calprotectin in children infected at baseline indicates that infection with H. pylori may exerts an adverse impact on intestinal health." (PMID 32324737, 2020). "Indeed, we did see a significant increase in the number of MPO-positive cells in the colon only during the ramp-up period, possibly indicating a transient increase of neutrophils during the earliest period following infection." (PMID 32119719, 2020). "As we did not observe any differences between numbers of neutrophils transmigrating into the infection site between wild-type and Stat2-/- mice but there was a difference in MPO levels in the colon contents of these mice, we next determined whether Stat2-/- neutrophils were functional." (PMID 31009517, 2019). "Upon infection, circulating neutrophils quickly initiate chemotactic interstitial migration reaching site of inflammation, and protect against microbial infections through multifaceted killing mechanism (ROS, myeloperoxidase/MPO, neutrophil extracellular traps/NETs)." (PMID 29868513, 2018).